RAB5A (RAB5A, member RAS oncogene family)
Description:
The small GTPases Rab are key regulators of intracellular membrane trafficking, from the formation of transport vesicles to their fusion with membranes. Rabs cycle between an inactive GDP-bound form and an active GTP-bound form that is able to recruit to membranes different sets of downstream effectors directly responsible for vesicle formation, movement, tethering and fusion. RAB5A is required for the fusion of plasma membranes and early endosomes and involved in early endocytic trafficking. Required for EEA1 recruitment to early endosomes. Recruits FERRY complex to early endosomes, where FERRY links early endosomes with a subgroup of mRNAs to enable mRNA intracellular distribution. Recruits RABEP1/Rabaptin-5 effector to early endosomes, thereby promoting endocytic membrane fusion (By similarity). Required for EGF and transferrin endocytosis and trafficking through early endosomes. Contributes to the regulation of filopodia extension. Required for the exosomal release of SDCBP, CD63, PDCD6IP and syndecan. Regulates maturation of apoptotic cell-containing phagosomes, probably downstream of DYN2 and PIK3C3 (By similarity).
Synonyms: RAB5
Tractability: Small molecule: a structure with a bound ligand is known; it has a high-quality binding pocket. Antibody: UniProt places it where antibodies can reach, with high confidence; its Gene Ontology location is reachable by antibodies, with medium confidence. PROTAC: ubiquitination databases record sites on it; its protein half-life has been measured.
Gene: Protein-coding gene on chromosome 3 (19,947,097 to 19,985,178, forward strand). Ensembl gene ENSG00000144566.
Subcellular location: Cell membrane; Early endosome membrane; Melanosome; Cytoplasmic vesicle; Cell projection, ruffle; Membrane; Cytoplasm, cytosol; Cytoplasmic vesicle, phagosome membrane; Endosome membrane
Subcellular location (Human Protein Atlas): Nucleoplasm; Vesicles
Pathways (Reactome):
Vesicle-mediated transport: Clathrin-mediated endocytosis; RAB GEFs exchange GTP for GDP on RABs; TBC/RABGAPs
Disease: Prevention of phagosomal-lysosomal fusion; Respiratory syncytial virus (RSV) attachment and entry
Hemostasis: Factors involved in megakaryocyte development and platelet production
Metabolism: Synthesis of PIPs at the plasma membrane
Metabolism of proteins: RAB geranylgeranylation
Gene Ontology:
Molecular function: G protein activity; GDP binding; GTP binding; GTPase activity; protein binding; guanyl nucleotide binding
Biological process: amyloid-beta clearance by transcytosis; canonical Wnt signaling pathway; early endosome to late endosome transport; endocytosis; endosomal transport; host-mediated perturbation of viral process; plasma membrane to endosome transport; positive regulation of exocytosis; protein localization to early endosome; receptor internalization; regulation of endosome size; regulation of filopodium assembly; regulation of synaptic vesicle exocytosis; synaptic vesicle recycling; membrane fusion; regulation of autophagosome assembly; regulation of long-term neuronal synaptic plasticity
Cellular component: cytoplasm; cytoplasmic side of early endosome membrane; cytoplasmic vesicle; cytosol; early endosome; early endosome membrane; endosome membrane; extracellular exosome; melanosome; membrane; plasma membrane; somatodendritic compartment; terminal bouton; axon; axon terminus; clathrin-coated endocytic vesicle membrane; dendrite; early phagosome; endocytic vesicle; endosome; neuronal cell body; phagocytic vesicle; synaptic vesicle; synaptic vesicle membrane; actin cytoskeleton; and 3 more
Genetic constraint (gnomAD): Loss-of-function variants: 3 observed, 19.62 expected, observed/expected ratio (o/e) 0.15, 90% interval 0.069 to 0.4. The upper end of that interval is the gene's LOEUF score, 0.4, which puts it in group 1 of 6, group 1 being the genes least tolerant of losing a copy. Missense variants: 123 observed, 197.14 expected, observed/expected ratio (o/e) 0.62, 90% interval 0.54 to 0.73. Synonymous variants: 78 observed, 69.28 expected, observed/expected ratio (o/e) 1.13, 90% interval 0.94 to 1.36.
Homologues: Orthologues: chimpanzee RAB5A (100% identical), dog RAB5A (99% identical), rabbit RAB5A (99% identical), guinea pig RAB5A (98% identical), mouse Rab5a (98% identical), pig RAB5A (98% identical), rat Rab5al1 (98% identical), rat Rab5a (97% identical), tropical clawed frog rab5a (93% identical), zebrafish rab5aa (93% identical), zebrafish rab5ab (92% identical), macaque RAB5A (90% identical). Paralogues in human: RAB5C (88% identical), RAB5B (81% identical), RAB17 (44% identical), RAB22A (41% identical), RAB11A (41% identical), RAB11B (41% identical), RAB21 (41% identical), RAB31 (40% identical), RAB1A (40% identical), RAB1B (40% identical), RAB26 (40% identical), RAB6B (40% identical), and 56 more.
Diseases named in the same sentence as RAB5A in open-access papers:
RAB5A is named in the same sentence as 118 diseases in open-access papers, as found by Europe PMC text mining. Sharing a sentence is not in itself a finding about the gene and the disease. The quoted sentences say what the papers report.
breast carcinoma (32 papers, 2012 to 2025). "Similar graded expression of RAB5A associated with elevated γH2AX and cGAS was also detected in patient-derived breast cancer organoids." (PMID 36581770, 2023). "By in silico analysis, Rab5A is found to be associated with poor prognosis in HR+ breast cancer [HR = 1.3 (1.01-1.6), P = 0.037] in multivariate analysis among tumors with Rab5A expression > 75% percentile." (PMID 35582035, 2021). "Blockade of Rab5a activation can be a potential therapeutic approach to restrict MVs shedding and associated breast cancer metastasis." (PMID 29743547, 2018). "Since Rab5A was also reported to be associated with lymph node metastasis in breast cancer patients, the reduction of this protein upon CB agonist exposure suggested the potential obstruction of breast cancer metastasis in the presence of CB agonists." (PMID 39527598, 2024). "In our previous study, we focused on RAB5A and its role in the development of breast cancer, especially TNBC." (PMID 38470169, 2024). "Consistent with the mechanistic data linking these molecules functionally, these analyses demonstrate that ITGB6, GDI2, and RAB5A expression positively correlate in patients with HER2+ breast cancer." (PMID 39630893, 2024). "Our results revealed the reduction of Rab5A in MDA-MB-231 breast cancer cells exposed to individual or the combination of CB agonists associated with the reduction in cell invasion and lamellipodia formation in this study." (PMID 39527598, 2024). "Even though the number of patients is small, our clinical data from I-SPY2 also illustrates the possibility to define a RAB5A expression threshold to determine T-DM1 treatment in HER2-expressing breast cancer patients." (PMID 34741021, 2021). "Suppressed autophagy on the account of miR-101 is reported in breast cancer (targeting RAB5A, STMN1 and ATG4D), HCC (through EZH2) and in ischemic liver (via activating mTOR signaling pathway)." (PMID 32124227, 2020). "Rab5A protein expression was correlated to enhanced migration of breast cancer cells and lymphatic dissemination in human breast cancer specimens." (PMID 32823947, 2020). "Overexpression of RAB5A is an indicator of poor prognosis in hepatocellular carcinoma, pancreatic cancer and estrogen receptor positive breast cancer." (PMID 30650664, 2019). "Rab5a has been shown to be involved in cellular functions as an oncogene, and overexpression of miRNA-130a inhibits proliferation and apoptosis of breast cancer cells through Rab5a targeting." (PMID 31640738, 2019). "In this study, we demonstrate that trypsin-mediated cleavage of PAR2 leads to the generation of pro-metastatic MVs from human breast cancer cells via the activation of Rab5a." (PMID 29743547, 2018). "Data showed that Rab5a expression is quite higher in breast cancer tissues as compared to normal tissues which are also accompanied by a relative higher expression of PAR2 in the cancer tissues." (PMID 29743547, 2018). "In addition to Rab5A, two proteins associated with cell motility, focal adhesion formation and cell-cell adhesion including ACTBL2 and CTNNA2 were also downregulated in breast cancer cells exposed to CB agonists." (PMID 39527598, 2024). "Pan and colleagues could demonstrate in their tumor samples that RAB5A was upregulated and miR-130a was downregulated in breast cancer tissues and cells." (PMID 35409043, 2022). "Both C28 and C5 expressed reduced levels of the RABs, and this was more pronounced in C5 although we did not detect changes in RAB5A that has been linked to breast cancer metastasis." (PMID 30980596, 2019). "Correlation between RAB5A expression and T-DM1 sensitivity is confirmed in breast cancer patients treated with trastuzumab emtansine/pertuzumab in the I-SPY2 trial (NCT01042379), but not in the trastuzumab/paclitaxel control arm." (PMID 34741021, 2021).
breast carcinoma (continued). "To determine the metastatic potential of our MVs generated via Rab5a activation by trypsin from MDA-MB-231 cells, we incubated these MVs with a less metastatic, less aggressive human breast cancer cell line MCF-7." (PMID 29743547, 2018). "If low RAB5A can be used not only to deselect patients for T-DM1 but also to find those patients most likely to benefit from trastuzumab, it would be an improvement for future personalized HER2-positive breast cancer therapy." (PMID 34741021, 2021). "Moreover, we noticed that Rab5a and PAR2 are over-expressed in human breast carcinoma tissues as compared to normal breast tissues." (PMID 29743547, 2018).
Alzheimer disease (15 papers, 2012 to 2025). A progressive, neurodegenerative disease characterized by loss of function and death of nerve cells in several areas of the brain leading to loss of cognitive function such as memory and language. "Nerve growth factor (NGF) loss is a potential factor for the degeneration of basal forebrain cholinergic neurons (BFCNs) in Alzheimer's disease (AD), and Rab5a is a key regulatory molecule of NGF signaling transduction." (PMID 38780008, 2024).
viral infection (15 papers, 2011 to 2025). "RAB5A belongs to the Rab-GTPase family of proteins, plays an important role in endocytosis, exocytosis, and vesicle transport, and has been implicated in a large range of diseases ranging from cancer to bacterial and viral infections." (PMID 35059464, 2022). "Further studies showed that TMEM239 interacted with the early endosomal marker Rab5A, and that TMEM239 deletion affected the co-localization of viral capsid p72 and Rab5A shortly after viral infection." (PMID 39024394, 2024). "We have also discovered a new mechanism by which RSV uses Rab5a to suppress epithelial antiviral immunity, such that silencing of Rab5a results in reduced viral infection." (PMID 33504607, 2021). "Many studies have focused on Rab5a, however, few have investigated Rab5c, especially on the impact of virus infection and cellular immune responses." (PMID 33013900, 2020).
lung carcinoma (11 papers, 2012 to 2025). "PIK3CA, XIAP and Rab5a have previously been reported in lung cancer and we have reported the effect of the rest of the mentioned genes for the first time." (PMID 23874428, 2013). "Among them, overexpression of Rab5a, a canonical marker of early endosomes, is observable in lung cancer and hepatocellular carcinoma." (PMID 22796207, 2012). "On the contrary, those G-proteins, such as RAB5A, HRAS, and NRAS, that are modified either by two polyisoprenyl groups or a polyisoprenyl group and lipid thioester were relatively unaffected in lung cancer A549 and NCI-H1299 cells." (PMID 38540084, 2024).
melanoma (11 papers, 2015 to 2026). A malignant, usually aggressive tumor composed of atypical, neoplastic melanocytes. "Other Rab members, Rab1A, Rab5A, Rab7 and Rab27A, have been shown to be highly expressed in melanoma cells." (PMID 34401050, 2021).
hepatocellular carcinoma (10 papers, 2012 to 2026). A malignant tumor that arises from hepatocytes. "RAB5A, overexpressed in hepatocellular carcinomas, seems to be determinant for liver cancer progression, as suggested by the finding that a dominant negative form of RAB5A attenuates EGF-mediated signalling and cell migration of a human hepatoma cell line." (PMID 22724020, 2012). "RAB5 has three isoforms (RAB5A, B, and C), and its expression is elevated in non-small-cell lung cancer, hepatocellular carcinoma, and ovarian cancer." (PMID 28103577, 2017).
ovarian carcinoma (10 papers, 2012 to 2024). A malignant neoplasm originating from the surface ovarian epithelium. "In keeping with the potential of miR-101 to regulate autophagy and ovarian cancer progression, it is to be mentioned that its target RAB5A was shown to be upregulated and to promote cell proliferation in ovarian cancer." (PMID 24877083, 2014). "Rab5a being activated by Appl1 is significantly overepressed in ovarian cancer and is connected with lung, hepatocellular and stomach carcinomas." (PMID 23874428, 2013). "Of note, stathmin over-expression showed a significant association with poor prognosis in ovarian cancer patients, and Rab5A was shown to promote cell proliferation in ovarian cancer." (PMID 22974323, 2012). "RAB5A belongs to the Ras family of G proteins, which mainly regulates vesicle transport and is involved in the development of many human cancers, which can promote tumor proliferation and distant metastasis, including breast, liver, lung, pancreatic, and ovarian cancers." (PMID 39323841, 2024). "RAB11A involves the regulation of the Wnt/β-catenin pathway to promote the deterioration of prostate cancer, and RAB5A upregulation is related with the proliferation invasion and EMT of ovarian cancer." (PMID 36438897, 2022). "Of the three proteins investigated (RAB4A, RAB5A, and RAB11A), only RAB5 expression was found to correlate with T-DM1 toxicity in a cell line panel of HER2-positive breast and ovarian cancer." (PMID 34741021, 2021). "In ovarian cancer, the knockdown of circ-0001756 could suppress IGF2BP2 mediated RAB5A expression, thus inhibiting malignant progression of ovarian cancer." (PMID 38637813, 2024). "For instance miR-101, reported to act as inhibitor of autophagy in breast cancer by targeting STMN1, RAB5A, and ATG4D mRNAs, has been found downregulated also in ovarian cancer compared to normal tissue, and its reexpression exerted tumour-suppressive effects in ovarian carcinogenesis." (PMID 24877083, 2014).
colorectal cancer (8 papers, 2020 to 2025). A primary or metastatic malignant neoplasm that affects the colon or rectum. "Ras-related protein Rab-5A (RAB5A) was previously indicated to be overexpressed in oral cancer, cervical cancer tissue and in colorectal cancer." (PMID 36979661, 2023). "It was noteworthy that mefloquine hydrochloride, an antimalarial drug, was identified as a novel RAB5A inhibitor and could efficiently disrupt the tumourigenic activity of colorectal cancer stem cells." (PMID 37203239, 2023). "Increased expression of RAB5A predicts metastasis and shorter OS in colorectal cancer patients." (PMID 34078402, 2021). "Furthermore, activation of RAB5A promotes colorectal cancer progression." (PMID 40381373, 2025).
pancreatic cancer (7 papers, 2014 to 2026). "High RAB5A expression increased pancreatic cancer cell migration through increased filopodia formation." (PMID 40381373, 2025). "Expression of RAB5A correlated with pancreatic tumor progression in another study of 111 patients as well." (PMID 34078402, 2021). "Among 39 differentially expressed factors, seven up-regulated genes (CAV2, CIDEC, HILPDA, HSD17B11, NCEH1, RAB5A, and SQLE) and two down-regulation genes (BSCL2 and FITM1) were significantly associated with overall survival of pancreatic cancer patients." (PMID 34078402, 2021). "We further identified that enhanced expression of 7 genes namely CAV2, CIDEC, HILPDA, HSD17B11, NCEH1, RAB5A, and SQLE are associated with significantly shorter overall survival whereas elevated expression of BSCL2 and FITM1 correlates with longer overall survival of pancreatic cancer patients." (PMID 34078402, 2021).
cervical cancer (6 papers, 2011 to 2025). A primary or metastatic malignant neoplasm involving the cervix. "In the present study, we investigated the effect of Rab5a on cervical cancer invasion and metastasis and the molecular mechanism underlying the involvement of Rab5a." (PMID 21849022, 2011). "A previous study has shown that Rab5a expression is increased in cervical cancer tissues, and Rab5a knockdown markedly inhibits cancer cell proliferation and invasion." (PMID 38695990, 2024). "Rab5a expression was assessed by immunohistochemical analysis on a cervical cancer tissue microarray." (PMID 21849022, 2011). "In the present study, we investigated the mechanism of Rab5a involving in the progression of cervical cancer cells invasion and metastasis." (PMID 21849022, 2011). "Here we report that Rab5a involves in the progression of cervix cancer." (PMID 21849022, 2011). "We found that Rab5a was expressed at a high level in cervical cancer tissues." (PMID 21849022, 2011). "Taken together, these data suggest that Rab5a functions in regulating the invasion phenotype, and we propose that this regulation may be via integrin-mediated signaling pathway in cervical cancer cells." (PMID 21849022, 2011). "The results indicate that Rab5a may be involved in the progression of cervical cancer." (PMID 21849022, 2011). "Mechanistically, the absence of Rab5a expression downregulates the assembly and activities of integrins and the downstream signaling molecules in cervical cancer cells, including phosphorylation of FAK and paxillin." (PMID 38695990, 2024). "The results showed that Rab5a expression was up-regulated in cervical cancer as compared with paired non-tumorous tissues." (PMID 21849022, 2011). "In this paper, we confirmed that Rab5a protein was over expressed in cervical cancer compared to the paired non-tumorous tissues." (PMID 21849022, 2011). "To determine the expression pattern of Rab5a protein in cervical cancer, we analyzed Rab5a expression by immunohistochemistry in primary cervical cancer tissues and paired adjacent non-tumorous tissues from 31 patients (62 tissue cores)." (PMID 21849022, 2011). "Moreover, the absence of Rab5a expression reduced the levels of integrin-mediated signaling molecules in cervical cancer cells, thereby decreased cancer cell motility and invasiveness." (PMID 21849022, 2011).
COVID-19 (6 papers, 2020 to 2025). A disease caused by infection with severe acute respiratory syndrome coronavirus 2. "Furthermore, RAB5A is a key host protein for interaction with SARS-CoV-2 and may be an important target for inhibiting COVID-19 progression." (PMID 34975885, 2021).
gastric cancer (6 papers, 2017 to 2024). A primary or metastatic malignant neoplasm involving the stomach. "It was reported that the knockdown of Rab5a or CCL2 could stimulate autophagy to reverse cisplatin resistance in gastric cancer." (PMID 33516270, 2021).